INS (insulin)
Diseases named in the same sentence as INS in open-access papers (continued):
Sharing a sentence is not in itself a finding about the gene and the disease.
diabetes (continued). "The use of diabetes technologies such as continuous subcutaneous insulin infusion (CSII), CGM, and hybrid closed-loop (HCL) systems has led to improvements in glycemic control." (PMID 38694495, 2024). "In the context of insulin resistance, impaired insulin signaling pathways lead to elevated blood glucose levels, disrupted glucose and lipid metabolism, and the exacerbated progress of diabetes." (PMID 39459158, 2024). "Community‐based studies have also shown a decrease in amylase with an increase in plasma insulin and insulin resistance, prior to the progression to overt diabetes." (PMID 38955666, 2024). "Known diabetes was reported in 60% of the patients, Type 2 diabetes (70%) being the most common type of diabetes, and 55.6% reported taking insulin." (PMID 39060948, 2024). "In contrast, T2DM, accounting for about 90% of diabetes cases, arises from reduced tissue sensitivity to insulin, resulting in insulin resistance, hyperglycemia, and insulin deficiency." (PMID 39682954, 2024). "Successful oral insulin administration can considerably enhance the quality of life (QOL) of diabetes patients who must frequently take insulin injections." (PMID 38167129, 2024). "Though insulin therapy remains the standard treatment regimen, clinical trials of diabetes treatment in this unique group are warranted." (PMID 38792534, 2024). "Type 2 diabetes mellitus (T2DM) is characterized by a combination of impaired insulin secretion and insulin resistance." (PMID 39683552, 2024). "This ultimately results in decreased insulin levels and the development of hyperglycemia, which are both key characteristics of diabetes mellitus." (PMID 39334723, 2024). "While the MDM group showed a slightly greater prevalence of insulin treatment, family history of diabetes, and history of DKA than the T2DM group, these differences were not statistically significant (P > 0.05)." (PMID 39749018, 2024). "Insulin icodec, with its unique molecular and pharmacological features, provides an innovative once-weekly treatment option for the treatment of diabetes mellitus, being one of the most important therapeutic innovations in the field." (PMID 38610878, 2024). "The depletion of XBP1 results in β-cell dysfunction, dedifferentiation, and heightened vulnerability to diabetes, underscoring its significance in maintaining β-cell homeostasis and regulating insulin secretion." (PMID 39057094, 2024). "The median age of the patient population was 65 years (IQR: 57–71), 69% were male, 49% had diabetes mellitus; of those, 27% were treated with insulin." (PMID 36821060, 2024). "Our findings also underscore the need for education and awareness tools for patients to adhere to prescribed insulin for improved diabetes management and prevention of complications such as DF." (PMID 38439010, 2024). "Recognizing the critical role of AI and connected devices in insulin therapy represents a pivotal shift in diabetes care which should be reflected in ongoing research and clinical practice." (PMID 39519579, 2024). "Type 2 diabetes mellitus (T2DM) is a complex chronic disease characterized by decreased insulin secretion and the development of insulin resistance." (PMID 39273144, 2024). "We validated three zebrafish larvae models that exhibited diabetes-like phenotypes, by measuring the BMI and adipose deposits, and glucose and insulin assays." (PMID 39621609, 2024). "Evading immune responses evoked by proinsulin antigens by deleting insulin genes has been shown to prevent diabetes in the NOD mouse, emphasizing the importance of this T cell subset as a potential therapeutic target." (PMID 38787820, 2024). "Currently, insulin injections, oral hypoglycemic drugs, and lifestyle management are the main treatments for diabetes." (PMID 39125375, 2024).
diabetes (continued). "Ketoacidosis occurred in 6 participants allocated to empagliflozin (including five participants on insulin, one of whom had type 1 diabetes, and one participant without diabetes) and one allocated to placebo (who was not taking open-label SGLT2 inhibitor)." (PMID 38061372, 2024). "Diabetes has a complex and multifactorial pathophysiology that includes insulin resistance, decreased pancreatic insulin secretion, and hormonal dysregulation in the enterohypothalamic and enteroinsular axes." (PMID 38892574, 2024). "When conventional antidiabetic drugs fail to control blood glucose levels in people with type 2 diabetes mellitus, insulin plays a pivotal role." (PMID 39211720, 2024). "Decompensation eventually occurs and insulin levels are decreased, leading to hyperglycemia and type 2 diabetes mellitus." (PMID 38846018, 2024). "CGM systems have revolutionized diabetes care by providing real-time glucose readings and enabling more precise insulin dosing." (PMID 39246894, 2024). "Administration of curcumin to mice fed with a high-fat diet (HFD) and induced diabetes improved the glycemic status and insulin sensitivity, reduced NF-kB in the liver, reduced macrophage infiltration into WAT, and increased adiponectin production." (PMID 39208245, 2024). "A decreased response to insulin and insufficient insulin production are two characteristics of diabetes mellitus type 2, also known as T2DM, a metabolic condition that lasts for a long time." (PMID 38846218, 2024). "In diabetes, pancreatic β-cells gradually lose their ability to secrete insulin with disease progression." (PMID 38613031, 2024). "For instance, children and adolescents diagnosed with type 1 diabetes mellitus are advised to follow dietary recommendations in addition to taking prescribed insulin." (PMID 39078826, 2024). "Puberty and adolescence are characterized by rapid endocrinological changes that result in an increase in insulin resistance, exposing individuals with diabetes to glycemic decompensation and requiring frequent and dynamic adjustments of insulin therapy." (PMID 39334618, 2024). "The generation of insulin-producing cells from human-induced pluripotent stem cells holds great potential for diabetes modeling and treatment." (PMID 38304198, 2024). "Treatment with 1,25(OH)2D improved insulin sensitivity via PPARγ in ovariectomized rats and reversed diabetes-induced downregulation of the insulin receptor in STZ-treated diabetic rats." (PMID 39339785, 2024). "CAM helps to manage diabetes, a significant risk factor for CVD, by improving insulin sensitivity and reducing blood glucose levels." (PMID 39599634, 2024). "Pancreatic cancer incidence was compared according to weighted cumulative exposures to GLP-1RA and to basal insulin in a Cox model implemented in discrete time, with time origin at 2 years after diabetes diagnosis, adjusting for confounding." (PMID 38175642, 2024). "Dietary fiber can improve postprandial blood sugar and long-term diabetes control, with grain dietary fiber enhancing insulin sensitivity." (PMID 38962677, 2024). "The majority of Brazilians who took part in the PNS reported using medication to control hypertension in the previous 15 days (91.5%) and using oral medication for diabetes (95.2%) and/or insulin (70%)." (PMID 39292136, 2024). "Patients with diabetes mellitus will ultimately need insulin 8 years–10 years after the diagnosis of diabetes to maintain a desirable level of glycaemic control." (PMID 38694587, 2024). "One of the recent advances in diabetes treatment is the discovery of the incretin-insulin pathway, which involves two hormones: glucagon-like peptide-1 (GLP-1) and glucose-dependent insulinotropic polypeptide (GIP)." (PMID 38523307, 2024).
diabetes (continued). "To infer a causal relationship between AS and various diabetes-related traits, including type 1 diabetes (T1DM), T2DM, blood glucose levels, fasting glucose, glycated hemoglobin, and fasting insulin, we employed Mendelian randomization (MR) analysis." (PMID 39649224, 2024). "In the development of diabetes and obesity, GMEVs can alter the permeability of the gut barrier and induce intestinal inflammation, increasing insulin resistance and triggering inflammation." (PMID 39085351, 2024). "Glycemic control improved, with statistically significant reductions in insulin, HbA1c, and glucose levels, and complete remission of type 2 diabetes mellitus in affected patients." (PMID 39852200, 2024). "The DIATEC trial will show the effects of in-hospital CGM in combination with diabetes teams and operational insulin titration algorithms to act on CGM data in managing hospitalised patients with type 2 diabetes." (PMID 38711112, 2024). "Adolescents also expressed psychological difficulties managing their own care, including a dread of needles, forgetting to take their insulin, feeling ashamed, and thinking that having diabetes was a burden in their lives." (PMID 39315319, 2024). "One study reported risk factors for RSV infection and these included being a female, odds ratio (OR): 4.98 (95% confidence interval [CI]: 1.62–15.33); chronic heart failure, OR: 2.31 (1.13–4.73), and diabetes requiring insulin, OR: 9.82 (2.20–43.90)." (PMID 39284784, 2024). "Diabetes management is conducted through treatment with insulin, oral hypoglycemic drugs, regular physical activity, healthy diet, and psychosocial care." (PMID 39857342, 2024). "While stress-related disorders affect the nervous system and the body’s reaction to stress (American Institute of Stress, 2023), diabetes primarily affects the endocrine system, specifically insulin regulation and blood sugar control." (PMID 39224824, 2024). "Since insulin is a hormone that regulates blood sugar, hyperglycemia is a consequence of uncontrolled diabetes, which can induce significant damage to several body systems, especially nerves and blood vessels." (PMID 39456481, 2024). "AMPK has been shown to have beneficial effects in insulin-resistant states such as diabetes and nonalcoholic fatty liver disease in obesity." (PMID 38195611, 2024). "Other studies have shown that the insulin sensitivity of patients with MD is impaired, leading to increased blood sugar, and eventually leading to diabetes." (PMID 39268231, 2024). "These barriers can lead to significant delays and/or interruptions in insulin administration, exposing patients to higher risks of unbalanced diabetes complications." (PMID 38213906, 2024). "Participants with diabetes treated with insulin were younger (median [IQR] age 72.1 [63.2–79.3] years) than tablet-treated participants (74.1 [64.6–81.1] years) and diet-treated participants (77.0 [67.5–84.1] years)." (PMID 39358593, 2024). "Conversely, diabetes often leads to increased blood KBs due to low insulin and high counterregulatory hormone levels." (PMID 39262573, 2024). "Diabetes: Elevated levels of insulin can promote cellular proliferation and reduce apoptosis, thus facilitating the development and progression of mammary neoplasms." (PMID 38699635, 2024). "In summary, various intestinal microbial metabolites participate in the pathogenesis of diabetes by regulating insulin secretion and sensitivity." (PMID 38248846, 2024). "Insulin is generally essential therapy for those with T1D, and it is recommended for those with T2D whose blood glucose is uncontrolled while on other diabetes therapies." (PMID 36992575, 2024). "Improved glucose levels were also observed in PWD following insulin dose adjustment as per the suggestions of a diabetes nurse educator." (PMID 38338237, 2024). "Over the past few decades, numerous insulin analogs have been developed for the treatment of diabetes and to prevent its complications." (PMID 39170740, 2024).
diabetes (continued). "Diabetes mellitus is one of the metabolic diseases characterized by hyperglycemia resulting from defects in insulin secretion, insulin function, or both." (PMID 38673584, 2024). "Previous research emphasized that diabetes and AD share numerous common cellular and molecular pathways, including impaired insulin signaling, chronic hyperglycemia, and inflammatory effects." (PMID 39247877, 2024). "Enhancing these processes can potentially reverse diabetes, reducing the need for external insulin therapy." (PMID 39057094, 2024). "Linagliptin is a class drug for the treatment of type 2 diabetes mellitus that can promote the release of insulin from pancreatic islet β-cells and inhibit the secretion of glucagon by pancreatic α-cells." (PMID 38762508, 2024). "Further histological staining showed that SF-DFO partially inhibited STZ-induced pancreatic β cell apoptosis and promoted pancreatic β cell proliferation and pancreatic β cell mass and insulin expression in diabetes." (PMID 38945950, 2024). "HbA1c, number of medical phone calls, insulin dosing, and hospitalizations due to diabetes decompensation." (PMID 39867016, 2024). "In-depth studies looking into hormonal content within the pancreas in diabetics have reported findings of the reduction of insulin stores in the pancreas and glucagon stores that remained unchanged." (PMID 38665134, 2024). "We conducted a retrospective observational cohort study between 2020 and 2023 in 26 patients with type 1 and type 2 diabetes mellitus (DM) who were using 3-4 injections per day of insulin and were monitored by continuous glucose monitoring (CGM)." (PMID 38650779, 2024). "T1D care requires a complex daily regimen of blood glucose monitoring, tracking dietary intake, and administering insulin, with quarterly follow-up by diabetes specialty care providers." (PMID 39110496, 2024). "Regarding the pathophysiology of diabetes, there are studies investigating the therapeutic effect of curcumin in cases of insulin action, insulin secretion malfunction, β-cell dysfunction, insulin secretion reductions, and insulin resistance." (PMID 38922352, 2024). "Diabetes mellitus encompasses various metabolic disorders characterized by elevated blood sugar levels due to impaired insulin secretion or increased insulin resistance." (PMID 38673052, 2024). "High amounts of circulating 2-ketoisocaproic acid inhibit insulin-stimulated glucose transport in an mTORC-1-dependent manner, which contributes to insulin resistance and ultimately results in type 2 diabetes mellitus." (PMID 39456808, 2024). "Twenty-nine (10.3%) of the patients had a preexisting diagnosis of diabetes, of which all had type 2 diabetes and five (17.2%) required insulin at baseline." (PMID 38392055, 2024). "Despite the growing literature on diabetes and mood disorders, the connection between diabetes, insulin signaling, and OCD remains poorly understood." (PMID 39796465, 2024). "The characterization of each system was conducted, alongside the assessment of the in vitro release behavior of insulin in phosphate buffer solutions, followed by the quantification of the hypoglycemic impact in rat models with diabetes." (PMID 39771551, 2024). "Pharmacists are actively engaged in providing counseling to patients on diabetes mellitus, covering general management, medication frequency, and the appropriate storage and usage of insulin." (PMID 38476498, 2024). "For people with type 1 diabetes mellitus (T1D), in particular, the teenage years are also marked by changes in insulin sensitivity related to the hormonal changes of puberty." (PMID 38774897, 2024). "Alterations in the correct functioning of these channels lead to pathologies such as diabetes and obesity, both of which have a metabolic outset and can originate from an increase in peripheral and central insulin resistance." (PMID 38612888, 2024).
diabetes (continued). "Another study of 296 people with diabetes during the Hull, England flooding of 2008 only documented A1C decreasing among insulin-treated participants." (PMID 38232087, 2024). "Controlling body weight, especially for obese diabetes patients, can improve insulin sensitivity, contributing to the remission of diabetes." (PMID 38962677, 2024). "Diabetes was defined by either self-reported diagnosis, intake of antidiabetic drugs or insulin, or HbA1c ≥ 6.5%." (PMID 38316913, 2024). "Mytilene General Hospital provided insulin pen needles at all times to all patients attending our diabetes outpatient clinics." (PMID 39063405, 2024). "Alpha-lipoic acid (ALA) is used in the comprehensive management of diabetes mellitus due to its antioxidant and pro-oxidant properties that affect insulin sensitivity and secretion." (PMID 39408316, 2024). "Insulin pumps, or continuous subcutaneous insulin infusion systems, were the first major step in diabetes technology advancement." (PMID 39065641, 2024). "In this case, diabetes has developed in her second decade of life, with high blood glucose requiring insulin." (PMID 38883102, 2024). "Diabetes is a lifelong and chronic disease with a defect in insulin function, insulin secretion, or both." (PMID 38910237, 2024). "The OGTT is the gold standard for diagnosing diabetes because it mimics the physiological glucose and insulin dynamics seen after a meal." (PMID 39274417, 2024). "Two, characterizing serum and plasma markers (resorption CTX, formation P1NP, sclerostin, insulin, insulin-like growth factor 1, IL-6, TNFα, etc.)would identify potential metabolic pathways by which diet and diabetes lower the fracture resistance of bone." (PMID 39012489, 2024). "An earlier switch to insulin-based diabetes management was observed in BC/RCC compared to matched individuals with type 2 diabetes but no cancer." (PMID 39020360, 2024). "South Asians develop diabetes and its related complications at an early age due to low BMI, smaller waist circumference, increased insulin resistance, and ectopic fat deposition as compared to Caucasians." (PMID 39257882, 2024). "The Whitehall II study further supports these findings, demonstrating that insulin secretion increases three to four years prior to the diagnosis of diabetes as a compensatory response to insulin resistance." (PMID 38370356, 2024). "The combination of prandial and basal insulin is a well-established strategy in diabetes management; however, its effectiveness in the context of RMS requires continuous evaluation." (PMID 38542117, 2024). "In some sources, we can find information about the MI’s ability to control insulin activity, improve insulin sensitivity, and has salutary effects in people with diabetes." (PMID 38999746, 2024). "Exercise interventions have also been shown to improve body weight, insulin sensitivity, decrease medication and insulin use ​, and reduce or prevent vascular complications that occur with diabetes." (PMID 39407129, 2024). "The activation of NF-κB, TLR4, and mTOR leads to the attenuation of insulin signaling and insulin resistance in several tissues, which contribute to obesity-related complications, including diabetes and atherosclerosis." (PMID 39065815, 2024). "The chronic hyperglycemia observed in diabetes generates ROS, and levels of ROS above the critical threshold can result in β-cell dysfunction and/or death, reducing insulin secretion." (PMID 39194658, 2024). "On the contrary, other studies have reported lower levels of Metrnl in individuals with prediabetes, diabetes, or obesity and suggested that Metrnl levels negatively correlate with fasting blood glucose, fasting insulin, HOMA-IR, and HbA1c." (PMID 39279784, 2024). "These include a definition of T2DM as an energy surplus-induced diabetes characterized by the gradual decline of β cell insulin secretion function, which ultimately aims to prevent the onset of severe obesity through mechanisms of weight loss." (PMID 39873003, 2024).